FOXP3 (forkhead box P3)
Diseases named in the same sentence as FOXP3 in open-access papers (continued):
Sharing a sentence is not in itself a finding about the gene and the disease.
lymph node metastasis (68 papers, 2008 to 2026). "Low FOXP3 TIL count was associated with reduced survival in univariate analysis in lymph node metastases (p = 0.011; log-rank test)." (PMID 39883679, 2025). "The results indicated that large tumor diameter, poor tumor differentiation, deep tumor invasion, lymph node metastasis, and high expression of PD-1, PD-L1, FOXP3, and CD25 were independent risk factors for EC prognosis (P < 0.05)." (PMID 40587482, 2025). "Contrary to our findings, FOXP3 overexpression has been associated with lymph node metastasis and shorter overall survival in OSCC and tongue carcinoma." (PMID 40806346, 2025). "-High RORγT/CD3 linked to lymph node metastasis (p = 0.002).-Foxp3/CD3 ratio linked to tumor localisation.-RORγT/CD3 ratio: independent prognostic marker (p = 0.04; HR 1.84)." (PMID 40650089, 2025). "A positive expression of Treg FoxP3 and lymph node metastasis were associated with a higher risk of death based on multivariate analysis." (PMID 38928083, 2024). "Our findings revealed that the recruitment of CD4+CD25+FOXP3+ Tregs at the tumor site was associated with an advanced‐stage and lymph node metastasis, and up to 70.9% of patients with high CD4+CD25+FOXP3+ Tregs infiltration showed lymph node metastasis." (PMID 39264227, 2024). "A total of 81% of the patients presented a positive Treg FoxP3 expression, being correlated with a higher risk of lymph node metastasis, tumor relapse, and death." (PMID 38928083, 2024). "These researchers also discovered a link between FOXP3 expression and lymph node metastases, suggesting that FOXP3 expression was associated with a poor prognosis." (PMID 37621817, 2023). "FOXP3+ Treg infiltration was also associated with invasion depth, lymph node metastasis, distant metastasis, and TNM stage." (PMID 33062072, 2020). "We found that Foxp3 expression was significantly associated with lymph node metastasis and clinical outcome in OSCC." (PMID 27457382, 2016). "The density of CD8+ TIL was positively correlated with lymph node metastasis, while the density of Foxp3+ TIL was negatively associated with T stage (P < 0.05)." (PMID 20064222, 2010). "In addition, increased infiltration of FoxP3+ Treg cells was associated with lymph node metastasis, extrathyroidal infiltration, and multifocality in papillary thyroid microcarcinoma (PTMC)." (PMID 39534095, 2024). "In addition, FOXP3 expression was also associated with TNM-stage and lymph node metastasis, which was correlated with the interaction of FOXP3 and TLR4 in tumor cell escape and subsequent tumor progression." (PMID 38674427, 2024). "Furthermore, statistical analysis demonstrates that Foxp3 immunoreactivity is associated with some clinicopathological factors, such as clinical stage and lymph node metastasis (all P < 0.05)." (PMID 28923073, 2017). "Foxp3 protein expression was significantly associated with lymph node metastasis (P <0.01)." (PMID 27457382, 2016). "Thus, the loss in FOXP3 due to epigenetic change like methylation may serve as a potential biomarker in cases with lymph node metastasis." (PMID 34938323, 2021). "FOXP3 expression was significantly elevated in advanced disease features, including N2 lymph node metastasis (14.77 ± 9.42, p < 0.05), histological grade G3 (11.69 ± 6.73, p < 0.05), and stage IIIB (19.72 ± 4.15, p < 0.05)." (PMID 41375087, 2025). "Our findings revealed a significant positive association between the expression of PD-1, PD-L1, FOXP3, and CD25 with the depth of tumor invasion and the presence of lymph node metastasis (P < 0.05)." (PMID 40587482, 2025). "High expression of PD-1, PD-L1, FOXP3, and CD25, along with lymph node metastasis, were identified as independent prognostic risk factors (P < 0.05)." (PMID 40587482, 2025). "FOXP3, a marker of regulatory T cells (Tregs), showed a significant increase in expression with advancing cancer stages and in cases with lymph node metastasis and visceral pleural invasion." (PMID 41375087, 2025).
lymph node metastasis (continued). "A decrease in the number of CD8+ T cells, an increase in Foxp3+ Tregs, and an increased ratio of Foxp3+ Treg/CD4+ T cells are significantly associated with lymph node metastasis and prognosis." (PMID 40106761, 2025). "Expression levels of PD-1, PD-L1, FOXP3, and CD25 were found to be positively associated with the depth of tumor invasion and lymph node metastasis (P < 0.05)." (PMID 40587482, 2025). "In lymph node metastases there was a significant positive correlation between FOXP3 TIL counts and CD8, CD3 and PD-L1 TIL counts (Spearman correlation coefficient 0.59, 0.70 and 0.61, respectively, p < 0.05 for all)." (PMID 39883679, 2025). "FoxP3+ Tregs were found in PTC tumor tissues, and their infiltration was associated with disease stage and lymph node metastasis." (PMID 39534095, 2024). "An increase in the number of FoxP3+ Tregs was associated with late TNM stage and PTC lymph node metastasis." (PMID 39534095, 2024). "The lymphocytic FOXP3 expression was an age-related factor, whereas tumor FOXP3 expression was correlated with lymph node metastasis." (PMID 38674427, 2024). "CD4+CD25+FOXP3+ Treg infiltration was correlated with lymph node metastasis (p = 0.047), stage (p = 0.017), and lymphatic invasion (p = 0.004)." (PMID 39264227, 2024). "CD8+ TILs/CD4+CD25+FOXP3+ Treg ratio was significantly correlated with T1 + 2 (28/57, 49.1%), lymph node metastasis (26/49, 53.1%), Stage I + II (29/61, 47.5%), and venous invasion (16/28, 57.1%)." (PMID 39264227, 2024). "Our findings suggest that lymph node metastasis in ICC reflects a high metastatic potential mediated through immune suppression induced by FoxP3+ TILs." (PMID 35597869, 2022). "In the current study, we also found that the ratio between FoxP3+ and CD8+ TILs, i.e. the FCR, was associated with poor prognosis and lymph node metastasis in ICC." (PMID 35597869, 2022). "HLA class II on TILs was negatively associated with lymph node metastasis and positively correlated with programmed death-ligand 1 (PD-L1) on TILs (p<0.001) and multiple immune markers (CD3, CD4, CD8, FOXP3; p<0.001)." (PMID 34362829, 2021). "The methylated promoter region of FOXP3 cases demonstrating either the absence or presence of protein exhibited a statistically significant relation with Her 2 neu receptor (p = 0.004) and metastatic lymph node tumors (p = 0.01)." (PMID 34938323, 2021). "We found that in patients with axillary lymph node metastases, FOXP3 expression was correlated with survival: Patients with high levels of FOXP3 expression have a shorter OS." (PMID 31852159, 2019). "High Foxp3+ Tregs infiltration seems to correlate with smoking status instead of gender, histological type, lymph node metastasis status, tumor size, vascular invasion, lymphatic invasion and pleural invasion." (PMID 27153545, 2016). "Further, IDO1 positive breast tumours have a positive correlation with the density of immune suppressive Foxp3+ T regulatory cells and lymph node metastasis." (PMID 26646699, 2016). "In the current study, we uncovered a relationship between the expression of FOXP3 in intratumoral lymphocytes and adverse clinicopathological parameters, such as high histological grade, lymph node metastasis, and Her-2 expression." (PMID 26305693, 2015). "The present meta-analysis demonstrates that in the context of BC, intratumoral FOXP3+ Tregs positively correlated with adverse clinicopathological parameters such as histological grade, lymph node metastasis, ER- status, and Her-2+ status." (PMID 26305693, 2015). "There were several possible explanations for the correlation between FOXP3+ TILs and lymph node metastasis and poor survival." (PMID 26475790, 2015). "The meta-analysis of all involved studies on lymph node metastasis showed a significantly higher incidence of FOXP3+ TILs in the lymph node positive group relative to the lymph node negative group (OR = 1.305, 95 % CI [1.071, 1.590], I2 = 60.0 %)." (PMID 26475790, 2015).
lymph node metastasis (continued). "FoxP3 would allow them to escape from immune surveillance, thereby resulting in cancer progression such as lymph node metastasis." (PMID 24707483, 2014). "High numbers of intratumoral FOXP3+ Tregs significantly correlated with shorter OS (P = 0.021) and lymph node metastasis (P = 0.024), and was also an independent factor for adverse OS (P = 0.035)." (PMID 24040244, 2013). "Both CCR7 and FOXP3 expression were significantly correlated with lymph node metastasis (P = 0.009 and 0.024, respectively)." (PMID 24040244, 2013). "It was worth noting that both CCR7 and FOXP3 expression were significantly correlated with lymph node metastasis." (PMID 24040244, 2013). "The expression of IDO in PTs was positively linearly correlated to the density of Foxp3+ Tregs in PTs and TDLNs and was significantly higher in tumors of more advanced stages and with more extensive lymph node metastasis." (PMID 22110525, 2011). "The IDO expression was significantly upregulated in tumors of more advanced stages and with more extensive lymph node metastasis, and displayed positive linear correlation with the density of Foxp3+ Tregs." (PMID 22110525, 2011). "The expression of immunohistochemical markers (PD-L1, PD-1, CD4, CD8, FOXP3) was correlated with retrospective clinic pathological parameters (lymph node metastasis, distant metastasis, lymph node metastasis during follow-up, disease progression, disease-specific death)." (PMID 37932810, 2023). "In oral SCC, the expression of FOXP3 was positively related to lymph-node metastasis." (PMID 36235242, 2022). "However, the Treg-specific transcription factor FoxP3 was expressed at higher levels than in the lymph node metastasis of patient 1, and expression of immunosuppressive arginase was also relatively high." (PMID 32350591, 2020). "Moreover, PD-L1 expression level and FOXP3+ Treg infiltration correlated with lymph node metastasis, distant metastasis, and TNM stage." (PMID 33062072, 2020). "The expression of FOXP3 was positively correlated with Dukes staging and lymph node metastasis." (PMID 30013992, 2018). "Similarly, our data suggested Foxp3 expression is correlated with higher clinical stage and lymph node metastasis." (PMID 28923073, 2017). "Multivariate Cox regression analysis was performed stepwise including age, gender, primary tumor (colon or rectum), UICC (I/II or III/IV), depth of tumor invasion (T category 1/2 or 3/4), differentiation (1/2 or 3/4), lymph node metastasis (N category), Foxp3 (%), Treg (%), TGF-ß (%), and IL-10 (%)." (PMID 23382847, 2013). "Concurrent expression of IDO and Foxp3 in SLN correlated well with lymph node metastasis." (PMID 19604349, 2009). "Furthermore, a high level of FOXP3 is positively related to lymph-node metastasis." (PMID 36235242, 2022). "A meta-analysis has shown that FOXP3+ Tregs have a significant negative effect on overall survival (OS) in BC patients, and are associated with estrogen and progesterone receptor status, as well as with lymph node metastases." (PMID 34884993, 2021). "Across the entire cohort, intratumoral immune cell densities in lymph node metastases were higher than in bone metastases (CD3+, CD8+, FoxP3+ and CD20+ cells) or tumors located in the urinary tract (CD3+, FoxP3+ and CD20+ cells)." (PMID 35046958, 2021). "Significant variables in the univariate logistic regression (lymph node metastasis, PD-1 on TILs, PD-L1 on TILs, CD3, CD4, CD8, and FOXP3) were enrolled into the multivariate logistic regression model." (PMID 34362829, 2021). "The patients with axillary lymph node metastases with the concomitant CCL20 high expression and increased FOXP3+ TILs infiltration had the worst OS (P < .001)." (PMID 31852159, 2019). "The higher frequency of FoxP3+ Tregs and density ratios of A2aR/CD8+ T cells in GC tissue were also correlated with the cancer stage, lymph node metastasis, and distant metastasis." (PMID 31930120, 2019).
lymph node metastasis (continued). "We found that the frequency of intratumoral FoxP3+ Tregs and A2aR+CD8+ T cells was tightly correlated with the TNM stage (P=0.025 and 0.003), lymph node metastasis (P=0.046 and 0.025), and distant metastasis (P=0.015 and 0.020)." (PMID 31930120, 2019). "The density of both FoxP3+ Tregs and A2aR+/CD8+ T cells was higher in GC tissue compared to peritumoral normal tissue and significantly correlated with the TNM stage, lymph node metastasis, and distant metastasis of GC." (PMID 31930120, 2019). "The increasing CD4+CD25+FOXP3+ Treg percentage was also closely in accordance with the TNM staging and lymph node metastasis status, which is consistent with previous studies." (PMID 28253320, 2017). "We found a significant positive correlation between CD8+ and FOXP3+ T-cells, in concordance with another recent study on a cohort including stage III CMM patients with sentinel lymph node metastases." (PMID 28851300, 2017). "An increasing stromal FoxP3+ TIL infiltration was inversely correlated with UICC-stage (Pearson's correlation coefficient, r = -0.40; p = 0.001), number of lymph node metastases (r = -0.36; p = 0.009) and N category in general (r = -0.36; p = 0.023)." (PMID 19732435, 2009). "Low FOXP3 TIL count and negative tumour PD-L1 expression (cut off 1%) were both significantly associated with reduced survival in lymph node metastases." (PMID 39883679, 2025). "Univariate analysis revealed that tumor depth, lymph node metastasis, stage, lymphatic invasion, venous invasion, infiltration of CD8 and FOXP3, PD‐L1 TC, CD25, CD4+CD25+FOXP3+ Tregs, and the CD8+ TILs/CD4+CD25+FOXP3+ Tregs ratio were significantly associated with OS." (PMID 39264227, 2024). "Foxp3 levels are also higher in patients with CC with lymph-node metastasis than those without metastasis." (PMID 37508372, 2023). "Pairwise comparisons revealed that the densities of intratumoral CD3+ and FoxP3+ T cells were significantly higher in lymph node metastases compared to bone metastases (CD3+ cells: p=0.025; FoxP3+: p=0.0006) or tumors located in the urinary tract (CD3+ cells: p=0.022; FoxP3+: p=0.0041)." (PMID 35046958, 2021). "However, intratumoral FoxP3+ and CD20+ cell densities were higher in the lymph node metastases in four and five out of six patients, respectively." (PMID 35046958, 2021). "Additionally, a significant correlation was found between lymph node metastasis and the expression of HIF-1α (P = 0.029) or Foxp3 (P<0.001)." (PMID 23723999, 2013). "Similarly, the expression level of Foxp3 also lacked statistical significance in both infiltration depth and lymph node metastasis (p >0.05)." (PMID 39104717, 2024). "Foxp3 levels are also higher in patients with lymph node metastasis than those without metastasis." (PMID 37508372, 2023). "The results showed that an increase in the CD4+CD25+Foxp3+(Treg)/CCR5+ cell ratio was closely related to the invasiveness of tumors: the Treg/CCR5 ratio in the lymph node metastasis group and nonmetastasis group was 0.028 ± 0.007 and 0.024 ± 0.003, respectively, P = 0.035." (PMID 36033472, 2022). "However, in patients with no axillary lymph node metastasis, FOXP3 expression did not have a significant correlation with survival." (PMID 31852159, 2019). "Expression of Foxp3 was positive in 87.5% (14/16) cases that had lymph node metastasis, and the positive rate was significantly higher than the samples with the absence of lymph node metastasis (55.9%, 19/34)." (PMID 28923073, 2017). "Furthermore, six parameters of the patients (sex, smoking status, with or without COPD, TNM staging, lymph node metastasis status, and pathological type of tumour) and their association with the CD4+CD25+FOXP3+ Treg percentage were evaluated." (PMID 28253320, 2017).
lymph node metastasis (continued). "Among the six cases with synchronous skin and lymph node metastases, no obvious pattern of similarities or differences for CD8 or FOXP3 TIL counts was observed, while tumour cell PD-L1 expression was mostly negative in both skin and lymph nodes." (PMID 39883679, 2025). "The results revealed that the increasing CD4+CD25+FOXP3+ Treg percentage correlated closely with the TNM staging and lymph node metastasis status (P < 0.05), while no such relationship was observed with the sex or pathological tumour type (P > 0.05)." (PMID 28253320, 2017). "Additionally, the absence of lymph node metastasis was positively correlated with a high accumulation of CD3+, CD8+, or FoxP3+ T lymphocytes (p = 0.01, p = 0.004, and p = 0.003, respectively)." (PMID 34440038, 2021). "The patients with axillary lymph node metastases with the concomitant CCL20 high expression and increased FOXP3+ TILs infiltration had the worst overall survival (OS) (P < .001), In lymph node-negative breast cancer patients, the status of CCL20 and FOXP3 was not related to OS (P = .22)." (PMID 31852159, 2019).